EGFR (epidermal growth factor receptor)
Diseases named in the same sentence as EGFR in open-access papers (continued):
Sharing a sentence is not in itself a finding about the gene and the disease.
lung cancer (continued). "Both mRNAs in serum were significantly correlated with those in lung cancer tissues (p < 0.05 for hTERT; p < 0.05 for EGFR)." (PMID 21892326, 2008). "We show that MET is highly expressed in lung cancer, often concomitantly with epidermal growth factor receptor (EGFR), including H1975 cell line." (PMID 19238632, 2008). "In lung cancer, EGFR inhibitors have been shown to be efficient in tumors with activating mutations of the receptor." (PMID 18549475, 2008). "The copy numbers of hTERT mRNA (p < 0.01) and EGFR mRNA (p < 0.01) were significantly higher in the lung cancer patients than in the healthy individuals." (PMID 21892326, 2008). "This study on pulmonary malignancy also demonstrates the clinical usefulness of hTERT mRNA, especially when combined with EGFR mRNA as a novel tumor marker in primary lung cancer for early detection and diagnosis." (PMID 21892326, 2008). "This method would be useful for patients or ethnic groups in which drugs targeting EGFR in lung cancer are thought to be effective." (PMID 21892326, 2008). "These encouraging data have led to the initiation of clinical studies in lung cancer, evaluating the combination of erlotinib, an EGFR tyrosine kinase inhibitor, with bevacizumab, an anti-VEGF antibody." (PMID 17592499, 2007). "Through these efforts, it would be possible to individualise EGFR-TKI treatment for patients suffering from lung cancer." (PMID 17325698, 2007). "In this way, the survival benefit of EGFR-TKIs, especially gefitinib, should be demonstrated in future clinical trials in a defined subset of patients with lung cancer." (PMID 17325698, 2007). "The epidermal growth factor receptor (EGFR)-driven pathway is known to be one of the known important oncogenic signang cascades in lung cancer." (PMID 17956637, 2007). "Tyrosine kinase inhibitor therapy of TKI-sensitive lung cancers inactivates HER3 signalling and downstream PI3K/Akt signalling, but HER3 signalling in TKI-resistant lung cancers appears to be uncoupled from EGFR and resistant to inactivation by TKIs." (PMID 17667926, 2007). "Several authors have showed that the mutation or amplification of EGFR are associated with dramatic and sustained response to TKI in lung cancer." (PMID 17876336, 2007). "This correlation between BIM induction and EGFR TKI induced cell death was not limited to the in vitro environment as shown by Yixuang Gong and colleagues using two distinct transgenic mouse models of EGFR-driven lung cancer." (PMID 17973575, 2007). "Here we show that up-regulation of the BH3-only polypeptide BIM (also known as BCL2-like 11) correlated with gefitinib-induced apoptosis in gefitinib-sensitive EGFR-mutant lung cancer cells." (PMID 17973572, 2007). "The broad testing of EGFR-selective TKIs in cancers revealed a small subset of highly responsive lung cancer patients." (PMID 17667926, 2007). "The FDA has approved the use of two EGFR-targeted molecules, gefitinib ("Iressa" from Astra Zeneca) and erlotinib ("Tarceva" from Genentech/Roche) in the second- and third-line treatment of lung cancer." (PMID 17626639, 2007). "Treatment with epidermal growth factor receptor (EGFR) tyrosine kinase inhibitors (TKIs) leads to rapid and sustained tumor shrinkage in a subset of patients with non–small cell lung cancer (NSCLC)." (PMID 18030354, 2007). "It is also unclear the difference in EGFR TKI sensitivity between early stage lung cancers and widely metastatic cancers that have previously received cytotoxic chemotherapy." (PMID 17096850, 2006). "Treatment of lung cancers with the epidermal growth factor receptor (EGFR) inhibitor, gefitinib (Iressa), is promising in patients carrying point mutations in the EGFR kinase domain." (PMID 17031409, 2006).
lung cancer (continued). "True assessment of the accuracy of our gene expression profiles to predict sensitivity of lung cancers to EGFR TKI will require prospective testing in patients." (PMID 17096850, 2006). "The gene expression signature of EGFR TKI sensitivity displays significant biological relevance in lung cancer biology in that pertinent signalling molecules and downstream effector molecules are present in the signature." (PMID 17096850, 2006). "Using lung cancer cell lines as tumor surrogates, we sought to find gene expression patterns that can predict the sensitivity to EGFR tyrosine kinase inhibitors." (PMID 17096850, 2006). "We screened the EGFR in 469 resected tumours of patients with lung cancer, which included 322 adenocarcinomas, 102 squamous cell carcinomas, 27 large cell carcinomas, 13 small cell carcinomas, and five other cell types." (PMID 16552419, 2006). "Published data, and our own, demonstrate that lung cancer cell lines are differentially sensitive to EGFR inhibitors, likely reflecting dependency upon EGFR or related signalling pathways." (PMID 17096850, 2006). "Gefitinib, an orally active, quinazoline tyrosine kinase inhibitor selective for EGFR, has been proved to have a clinically significant antitumour activity in lung cancers, and is now approved for use in several countries, including Japan and the USA." (PMID 17088902, 2006). "We developed a novel methodology using both bioinformatics approaches and supervised learning methods to model sensitivity to EGFR inhibitors with gene expression data from lung cancer cell lines." (PMID 17096850, 2006). "In lung cancer, there are several key mechanisms for EGFR activation, such as overexpression of ligands, gene amplification and activating mutations." (PMID 16911776, 2006). "Epidermal growth factor receptor is, therefore, a promising molecular therapeutic target in various tumour types, including lung cancer." (PMID 15870831, 2005). "Gefitinib is the first “molecular-target agent” for lung cancer that inhibits the tyrosine kinase of the epidermal growth factor receptor (EGFR; also known as ERBB1)." (PMID 15696203, 2005). "Data on the response of patients with lung cancer have demonstrated that approximately 10–15% of patients with EGFR-positive lung carcinomas have a dramatic response to EGFR tyrosine kinase inhibitors." (PMID 16280056, 2005). "EGFR gene amplification has been described in oligodendrogliomas, glioblastomas, lung carcinomas, gastric carcinomas and, recently, breast carcinomas." (PMID 16280056, 2005). "In lung cancer, deregulation of EGFR is seen mainly in NSCLC: EGFR is highly expressed in NSCLC at levels varying from 32–80%." (PMID 15318946, 2004). "The prognostic role of epidermal growth factor receptor (EGFR) remains controversial in patients with lung cancer." (PMID 9662257, 1998). "The prognostic role of the epidermal growth factor receptor (EGFR) and the related receptor p185HER-2 in lung cancer is as yet undefined." (PMID 8679464, 1996). "This is exemplified by the distinct and broader spectrum of resistance mutations (e.g., at G12, G13, Q61, R68, Y96, H95) observed in KRASG12C-mutant NSCLC compared to the more uniform T790M-mediated resistance, which accounts for 50–60% of acquired resistance to EGFR-TKIs in EGFR-mutant lung cancer." (PMID 41541668, 2026). "While lung cancer in Asian never-smokers is enriched for some genomic alterations, most notably EGFR mutations, the basis for the observed ethnic and gender disparities in lung cancer spectra in never-smoking Asian individuals remains poorly understood." (PMID 42001483, 2026). "Targeting the HHLA2-KIR3DL3 axis, particularly in combination with EGFR tyrosine kinase inhibitors, may provide a rational precision immunotherapy strategy for EGFR-mutant lung cancer." (PMID 42266686, 2026). "Epidermal Growth Factor Receptor (EGFR) mutations are a major driver of nonsmall cell lung cancer (NSCLC), particularly among nonsmoking populations." (PMID 41799114, 2026).
lung cancer (continued). "Using the EP-derived orthotopic lung cancer model, we performed immune profiling in combination with multi-omics data from patient cohorts to elucidate the tumor microenvironment characteristics of EGFR-mutant LUAD." (PMID 41356800, 2026). "Single-cell transcriptomic profiling of epidermal growth factor receptor (EGFR)-mutant lung cancers reveals tumor-specific upregulation of BCL2L1 alongside downregulation of myeloid cell leukemia 1 (MCL1), a stoichiometric imbalance that buffers apoptotic susceptibility." (PMID 41362736, 2026). "For instance, a study on nonsmall-cell lung cancer revealed significant differences in survival rates and EGFR mutation frequencies between Asian and non-Asian patients treated with gefitinib." (PMID 40113261, 2025). "Among patients with LC, univariate regression analysis revealed that age ≥ 65 years, male, ex- or current smokers, pack-years ≥ 20, high level of fibrinogen, CPI ≥ 40, tumor EGFR wild-type, advanced lung cancer, and coexistence of COPD, IPF, or CPFE were related to poor survival." (PMID 40507634, 2025). "the frequency of EGFR mutant lung cancer incidence and increasing PM2.5 levels”." (PMID 40227422, 2025). "Notably, TET1 was identified, a gene reported as an EGFR-TKI-induced factor in lung cancers and glioblastomas, supporting the reliability of our approach." (PMID 40290805, 2025). "This is because astrocytes secrete glutamate, which induces the mGluR1 signal in cancer cells through the WNT-5a/PRICKLE1/RE1 silent transcription factor REST axis, and then mGluR1 interacts with the epidermal growth factor receptor (EGFR) of lung cancer cells in a glutamate-dependent manner." (PMID 41154659, 2025). "Notably, two key target variants, EGFR c.2369C > T and KRAS c.35G > T, are of clinical relevance for lung cancer." (PMID 40465784, 2025). "Assays typically survey driver mutations relevant to lung cancer biology and therapy resistance – such as KRAS, PIK3CA and EGFR – and clonal‐haematopoiesis (CH) genes like DNMT3A and TET2, which are monitored to distinguish tumour DNA from age‐related background variants." (PMID 40847555, 2025). "Importantly, we provide molecular and cellular evidence demonstrating that PYCR1 is functionally implicated in EGFR- and TLR-driven lung cancer progression, highlighting its potential as both a biomarker and a therapeutic target for lung cancer." (PMID 41254241, 2025). "However, SORT1 was considered as an anti-oncogene in lung cancer by inhibiting the EGFR signaling pathway." (PMID 40750784, 2025). "Furthermore, in EGFR-mutant lung cancer, combining WDR4 inhibitors with EGFR TKIs has shown potential in overcoming resistance." (PMID 40570022, 2025). "Previous case series and case reports suggest an increased occurrence of EGFR-mutated lung cancer in TB patients especially among women and never-smokers." (PMID 41141063, 2025). "The second hypothesis suggests that SCLC transformation can occur in ALK inhibitor-treated lung cancers or in wild-type EGFR or ALK NSCLC treated with immunotherapy; however, the exact mechanism remains unclear." (PMID 40248195, 2025). "Similarly, epidermal growth factor receptor (EGFR)-targeted therapies, such as cetuximab, have improved the prognosis for lung cancer patients." (PMID 39944617, 2025). "Furthermore, studies have revealed that the spatial distribution and stability of EGFR are crucial factors in regulating lung cancer progression." (PMID 39910656, 2025). "In this particular case, the histological type was adenocarcinoma with an EGFR mutation, and current literature does not report any association between the genetic subtype of lung cancer and the occurrence of intestinal metastasis." (PMID 40432924, 2025). "Then we confirmed the correlation between the effect of ginsenoside Rg3 and gefitinib when combined with EGFR content, and we examined EGFR protein and EGFR phosphorylation in lung tissues of different groups of mice with chemically induced primary lung cancer." (PMID 40732366, 2025).
lung cancer (continued). "Overcoming resistance to EGFR TKIs is crucial for improving treatment outcomes in lung cancer." (PMID 41425254, 2025). "EGFR is the gene most strongly associated with susceptibility to lung cancer, yet we do not find such variants in our cohort." (PMID 40430005, 2025). "αvβ3 integrin also contributes to TGF-β1-mediated EGFR-TKI resistance in EGFR-mutant lung cancer." (PMID 40243917, 2025). "As reported in lung cancer, we suggested that EGFR alteration could be a potential oncogenic driver, so in February 2024, osimertinib (80 mg daily), a third-generation EGFR tyrosine kinase inhibitor, was started as a second-line treatment." (PMID 40364160, 2025). "Therefore, shikonin, a natural PKM2 inhibitor, significantly promoted apoptosis and inhibited the proliferation of EGFR wild-type lung cancer cells when combined with gefitinib." (PMID 40535810, 2025). "This trial established a new standard of care for metastatic EGFR lung cancer." (PMID 40136350, 2025). "Understanding the interplay between EGFR signaling and EVs could open new opportunities for developing innovative strategies to fight lung cancer." (PMID 40210802, 2025). "However, no study has yet combined features from different regions (particularly peri-tumor regions) to predict the response to EGFR-TKIs or ICIs in lung cancer patients." (PMID 39833943, 2025). "Pulmonary cryptococcosis is a rare but important opportunistic fungal infection that may occur during epidermal growth factor receptor-tyrosine kinase inhibitor (EGFR-TKI) therapy for lung cancer." (PMID 40502915, 2025). "Despite their short treatment durations, afatinib and osimertinib may have potential clinical activity in patients with EGFR L861R‐positive lung cancer." (PMID 41350121, 2025). "Moreover, CD146 was shown to contribute to the cancer stemness phenotype in Epidermal Growth Factor Receptor-Tyrosine Kinase Inhibitor (EGFR-TKI) - resistant lung cancer cells." (PMID 40032820, 2025). "In lung cancer, triptolide enhances the efficacy of EGFR tyrosine kinase inhibitors such as gefitinib, erlotinib, and icotinib, which are standard targeted therapies for NSCLC with EGFR mutation cell carcinoma." (PMID 40490812, 2025). "Finally, to evaluate the predictive accuracy of DST in guiding therapeutic decisions for lung cancer patients, tumor cells were isolated from a treatment‐naive EGFR‐mutant NSCLC patient using the optimized CD45+ cell depletion enrichment method." (PMID 40525275, 2025). "In pancreatic and lung cancers, EGFR is required for full activation of Ras." (PMID 41132131, 2025). "Aspirin enhances the therapeutic effectiveness of gemcitabine in treating the pancreatic cancer, enhances cisplatin sensitivity in ovarian cancer, and improves the synergistic effect of EGFR inhibitor and anti-mitotic chemotherapeutic Vinorelbine on lung cancer cells." (PMID 40647457, 2025). "The EGFR genotype is critical for treatment decision-making in lung cancer; however, its testing results may be affected by tumor heterogeneity and biopsy procedures." (PMID 41247642, 2025). "This implicates interactions across genetic factors, EGFR mutations and environmental effects as potential causes of lung cancer in never-smokers." (PMID 40227422, 2025). "In the future, bispecific antibody or a combination of targeted therapies could be the therapeutic options in EGFR-comutated lung cancer patients." (PMID 40364160, 2025). "There is an urgent necessity to devise efficient tactics to tackle the inevitable development of resistance to osimertinib, which is a third‐generation epidermal growth factor receptor (EGFR) inhibitor used in treating EGFR‐mutant nonsmall cell lung cancer (NSCLC)." (PMID 39721017, 2025).
lung cancer (continued). "Additionally, SMARCB1 functions as a tumor suppressor by regulating EGFR gene expression and modulating cellular response to EGFR-TKIs in human lung cancer." (PMID 39971779, 2025). "Together, the combined inhibition of EGFR–YAP/TEAD may offer a strategy to reduce lung tumorigenesis by disrupting agrin‐EGFR mechanotransduction, uncovering a therapeutic vulnerability for EGFR‐addicted lung cancers." (PMID 40165020, 2025). "Haplotype analysis of EGFR gene in Chinese patients with Lung cancer." (PMID 40438325, 2025). "Indeed, DEK overexpression in vitro was associated with an increase in EGFR, KRAS, and vimentin levels in lung cancer cell lines and poor prognosis according to patient database analyses." (PMID 39852534, 2025). "It was clarified that the core components namely ismine, 5-hydroxy-7-methoxy-2-methylchromone, pluviine, and acetyllycoramine have multi-target mechanisms in mitigating lung cancer through the inhibition of AR, EGFR and ESR-1 proteins with involvement of 39 putative pathways." (PMID 39888361, 2025). "Furthermore, in EGFR-mutant lung cancer cell lines, scRNA-seq analysis revealed changes in apoptosis-related gene expression following EGFR-TKI treatment." (PMID 40003951, 2025). "We discovered that CD16a/b shedding can be inhibited by a CD16a/b-targeting mAb (F9H4), which as consequence promotes NK cell-mediated cytotoxicity and interferon-γ production against lung cancer in the context of co-administration with two types of EGFR antibodies (cetuximab and necitumumab)." (PMID 41219228, 2025). "In summary, our findings suggest that combination therapy targeting HDAC5 may offer significant benefits for EGFR-mutant lung cancer patients treated with osimertinib." (PMID 40290805, 2025). "PM2.5 also activates the EGFR in lung cancer cells, including those with wild-type EGFR." (PMID 39578555, 2025). "Furthermore, liposomes conjugated with anti-EGFR aptamer-anchored chitosan effectively delivered erlotinib to lung cancer cells with high efficiency." (PMID 40124344, 2025). "In this model, EGFR or anaplastic lymphoma kinase (ALK) gene alterations, Karnofsky performance status (KPS) score, and the presence or absence of extracranial metastases are independent risk factors for the prognosis of LMs of lung cancer." (PMID 40484812, 2025). "Lung cancer epitomises precision oncology, which centers on targeting molecular alterations such as Epidermal Growth Factor Receptor (EGFR), Kirsten Rat Sarcoma Viral oncogene homolog (KRAS) G12C and Anaplastic Lymphoma Kinase (ALK), found in 40%–50% of lung adenocarcinomas." (PMID 41333367, 2025). "Given the intrinsic relationship between EGFR mutations and DDR, and the crucial function of DDR genes in the progression of lung cancer, w334e conducted a bioinformatics analysis to assess the predictive and prognostic significance of the associated DDR genes in patients with EGFRm NSCLC." (PMID 39994841, 2025). "For patients with lung cancer, we assessed the presence of EGFR mutations and found no clear association with anti-MET responses, as only 2 patients in the cohort had EGFR mutations, one of whom exhibited a response to MET." (PMID 40401526, 2025). "We, therefore, first tested whether agrin bestows stiffness‐dependent oncogenic potential in EGFR‐responsive lung cancer cell lines." (PMID 40165020, 2025). "Given the potential interplay between PYCR1 and these signaling pathways, we hypothesized that PYCR1 might be functionally associated with EGFR and TLR signaling in lung cancer." (PMID 41254241, 2025). "The availability of effective systemic options can tip the risk–benefit balance in favor of surgery – for example, resecting an intramedullary metastasis in a lung cancer patient responding to an EGFR inhibitor can prevent paralysis and yield survival beyond historically grim expectations." (PMID 40587076, 2025).